CCDC3 (coiled-coil domain containing 3)
Description:
Negatively regulates TNF-induced pro-inflammatory response in endothelial cells (ECs) via inhibition of TNF-induced NF-kappaB activation in ECs. Positively regulates lipid accumulation in adipose cells (By similarity).
Synonyms: DKFZp761F241
Tractability: Antibody: its Gene Ontology location is reachable by antibodies, with high confidence; UniProt places it where antibodies can reach, with medium confidence; UniProt predicts a signal peptide or a membrane-spanning region.
Gene: Protein-coding gene on chromosome 10 (12,896,625 to 13,099,652, reverse strand). Ensembl gene ENSG00000151468.
Subcellular location: Secreted
Subcellular location (Human Protein Atlas): Cytosol; Nucleoplasm; Predicted to be secreted
Gene Ontology:
Biological process: negative regulation of lipid metabolic process; negative regulation of tumor necrosis factor-mediated signaling pathway; signal transduction; negative regulation of gene expression
Cellular component: endoplasmic reticulum; extracellular region
Genetic constraint (gnomAD): Loss-of-function variants: 29 observed, 21.66 expected, observed/expected ratio (o/e) 1.34, 90% interval 0.99 to 1.79. The synonymous counts are far from expectation, so gnomAD's model fits this gene poorly and the ratio says little. Missense variants: 425 observed, 332.55 expected, observed/expected ratio (o/e) 1.28, 90% interval 1.18 to 1.38. Synonymous variants: 186 observed, 149.54 expected, observed/expected ratio (o/e) 1.24, 90% interval 1.1 to 1.4.
Homologues: Orthologues: chimpanzee CCDC3 (99% identical), macaque CCDC3 (99% identical), rabbit CCDC3 (94% identical), mouse Ccdc3 (90% identical), dog CCDC3 (90% identical), pig CCDC3 (90% identical), rat Ccdc3 (89% identical), tropical clawed frog ccdc3 (68% identical), zebrafish ccdc3a (64% identical), zebrafish ccdc3b (56% identical).
Diseases named in the same sentence as CCDC3 in open-access papers:
CCDC3 is named in the same sentence as 26 diseases in open-access papers, as found by Europe PMC text mining. Sharing a sentence is not in itself a finding about the gene and the disease. The quoted sentences say what the papers report.
atherosclerosis (2 papers, 2023 to 2025). A disease characterized by the build-up of fatty material and calcium deposition in the arterial wall resulting in partial or complete occlusion of the arterial lumen. "More remarkably, CCDC3 has been linked to human pathological disorders, such as atherosclerosis, inflammation, obesity, and cancer." (PMID 37263799, 2023). "Further investigating these possibilities would reveal more about how CCDC3 regulates chronic endothelial inflammation and consequent atherosclerosis, which will certainly be conducive to future development of anti-atherosclerotic therapies." (PMID 37263799, 2023). "Although it is still understudied, CCDC3, since its discovery, has been shown to play multiple roles in lipid metabolism, fatty liver, abdominal obesity, anti-inflammation, atherosclerosis, and cancer." (PMID 37263799, 2023). "Perhaps multiple cell types and tissues neighboring ECs can help prevent atherosclerosis in a collaborative fashion by enlisting CCDC3 paracrine function." (PMID 37263799, 2023). "Pursing this line of research further may unveil novel therapies against atherosclerosis by enlisting the anti-inflammatory capacity of CCDC3." (PMID 37263799, 2023).
breast carcinoma (2 papers, 2023 to 2024). "For example, CCDC3 was found to be a nuclear tumor suppressor in breast cancers, and CCDC60 is a potential marker correlated with the prognosis of head and neck squamous cell carcinoma." (PMID 38540995, 2024). "Recently, CCDC3 was also found to function as a nuclear tumor suppressor in breast cancers." (PMID 37263799, 2023).
colon cancer (2 papers, 2015 to 2017). "In the literature, the Coiled-coil domain containing 3 (CCDC3) represses tumor necrosis factor-α/nuclear factor κB-induced endothelial inflammation and the CELF2 is associated with T-cell signaling and it is also a suppressor gene of colon cancer." (PMID 26635870, 2015).
Hepatic steatosis (2 papers, 2017 to 2023). Steatosis is a term used to denote lipid accumulation within hepatocytes. "CCDC3 has been associated with abdominal obesity and both upregulation and downregulation of de novo lipogenesis and hepatic steatosis." (PMID 37263799, 2023). "Surprisingly, the transgenic (TG) mice ubiquitously overexpressing CCDC3 driven by a cytomegalovirus promoter exhibited relieved glucose intolerance, insulin insensitivity, and hepatic steatosis." (PMID 37263799, 2023). "CCDC3 TG mice displayed apparent improvement of HFD-induced hepatic steatosis compared to control mice." (PMID 28827783, 2017). "The results above suggest that CCDC3 might have a therapeutic effect on the development of fatty liver." (PMID 28827783, 2017). "By contrast, we did not observe any apparent liver steatosis in either of CCDC3 TG or control mice on chow diet at the same age." (PMID 28827783, 2017).
Obesity (2 papers, 2017 to 2023). Accumulation of substantial excess body fat. "This early study suggested that CCDC3 might play a hormone-like role in the regulation of lipid metabolism potentially involving obesity." (PMID 37263799, 2023). "A study showed that CCDC3 could repress TNF-α/NF-KB-induced a pro-inflammatory response in endothelial cells, suggesting a potential role for CCDC3 in the development of obesity and atherosclerosis." (PMID 28827783, 2017).
Abdominal obesity (1 paper, 2023). Excessive fat around the stomach and abdomen. "Furthermore, CCDC3 mRNA expression in human omental (but not subcutaneous) adipose tissues highly correlates with body mass index (BMI) and waist circumference, making CCDC3 a potential biomarker for abdominal obesity." (PMID 37263799, 2023).
cervical cancer (1 paper, 2023). A primary or metastatic malignant neoplasm involving the cervix.
endometritis (1 paper, 2020). An acute or chronic, usually bacterial infectious process affecting the endometrium. "This study confirmed differences in the expression profiles of six biomarkers in LPS-induced bovine endometritis: SLC7A5, COL1A1, AXIN2 (upregulated) and CFD, MGP, CCDC3 (downregulated)." (PMID 32545766, 2020). "The results revealed the dysregulation of the six crucial biomarkers involved in endometritis: SLC7A5, COL1A1, AXIN2 (upregulated); CFD, MGP, CCDC3 (downregulated)." (PMID 32545766, 2020).
Glucose intolerance (1 paper, 2017). Glucose intolerance (GI) can be defined as dysglycemia that comprises both prediabetes and diabetes. "CCDC3 alleviates glucose intolerance, insulin resistance and steatosis formation in transgenic CCDC3 mice on high-fat diet (HFD) by reducing the expression of hepatic PPARγ and its target gene CIDEA as well as other genes involved in de novo lipogenesis." (PMID 28827783, 2017). "Interestingly, glucose intolerance was improved in CCDC3 TG mice, although their insulin sensitivity was not altered in comparison with that of control mice." (PMID 28827783, 2017). "However, their glucose intolerance and insulin resistance induced by HFD were significantly reduced in CCDC3 TG mice compared to control mice." (PMID 28827783, 2017).
hepatic cancer (1 paper, 2017). "Among all the cells incubated in the Myc-CCDC3 media, liver cancer cells, such as Huh-7, HepG2 and PLC-PRF-5 cells, showed specific IF signals lined up on their cytoplasmic membrane." (PMID 28827783, 2017). "Interestingly, CCDC3, as a secreted protein, targets liver cancer cells and increases long chain polyunsaturated fatty acids, but decreases ceramide in the cells." (PMID 28827783, 2017). "Interestingly, we found that liver cell might serve as one main type of the target cells for CCDC3, because CCDC3 bound to the surface of liver cancer cells." (PMID 28827783, 2017). "Thus, we decided to first determine if CCDC3 could affect lipid metabolism in hepatic cancer cells by performing metabolomics analysis." (PMID 28827783, 2017).
myopia (1 paper, 2026). "Our meta-analysis identified seven novel suggestive loci associated with myopia progression, including FSTL5 on 4q32.2, SMARCA2 on 9p24.3, CCDC3 on 10p13, GALNT6/ACVR1B on 12q13.13, CRY1 on 12q23.3, ULK2 on 17p11.2, and MYL4/EFCAB13-DT on 17q21.32." (PMID 42094695, 2026).
psoriasis (1 paper, 2023). An autoimmune condition characterized by red, well-delineated plaques with silvery scales that are usually on the extensor surfaces and scalp. "However, Coiled-coil domain containing 3 (CCDC3) and palmdelphin (PALMD) have not been reported as known factors contributing to the development or progression of psoriasis." (PMID 38132145, 2023).
steatosis (1 paper, 2017). Increased lipid within the cytoplasm of cells. "Although the underlying mechanism(s) remains to be elucidated, we found that the significant decrease of PPAR-gamma and CIDEA mRNA levels in the livers of CCDC3 TG mice compared to that in control mice must account for the this anti-steatosis phenotype." (PMID 28827783, 2017). "Interestingly, HFD-induced fatty liver (steatosis) was also markedly alleviated in CCDC3 TG mice compared with control mice." (PMID 28827783, 2017). "Thus, we determined if CCDC3 might reduce HFD-induced steatosis by influencing the expression of these genes." (PMID 28827783, 2017).
cancer (3 papers, 2017 to 2025). A tumor composed of atypical neoplastic, often pleomorphic cells that invade other tissues. "Further studies on these cancer-associated CCDC3 mutations are necessary to unveil the role of CCDC3 in cancer initiation, development, and progression." (PMID 37263799, 2023). "Our analysis of CCDC3 mutations in cancer database revealed that the somatic mutation frequency of CCDC3 is 0.2%, including insertion, deletion, and point mutations." (PMID 37263799, 2023). "Would the cancer-derived CCDC3 C-terminal mutations have biological outcomes, such as promoting tumorigenesis and/or affecting immune response or lipid metabolism?" (PMID 37263799, 2023). "The inhibition of CCDC3 expression in PCa cell lines significantly inhibited cancer cell migration and invasion." (PMID 40843359, 2025). "Overexpression of CCDC3 in MCF-7, Cal51, and SKBR7 cells inhibited the proliferation of these BrC cells, whereas knockdown of CCDC3 in Cal51 cells by CRISPR led to the resistance to the anti-cancer drug, 5-FU." (PMID 37263799, 2023). "CCDC3 might also serve as a therapeutic agent for human cancers, such as BrC, because it is a short human polypeptide without any apparent toxicity in animals." (PMID 37263799, 2023). "This may provide an interesting avenue of research with regard to CCDC3, given its implication in multiple diseases including cancer, which will be discussed later." (PMID 37263799, 2023). "Therefore, whether CCDC3 promotes or suppresses cancer growth is likely context-dependent or cell-specific." (PMID 37263799, 2023). "Consistently with the results using cancer cells above, TAp63γ, but not p40, also induced the expression of CCDC3 mRNA in HUVEC." (PMID 28827783, 2017).
tumor (3 papers, 2022 to 2024). "Hence, CCDC family proteins, such as CCDC3, are studied for their potential implications in tumor suppression or progression." (PMID 37263799, 2023).
CCDC3 also shares sentences with these, for which no sentence is quoted: type 2 diabetes (2 papers); adenovirus infection (1); head and neck squamous cell carcinoma (1); immune deficiency (1); Insulin resistance (1); lung adenocarcinoma (1); metabolic disorders (1); prostate carcinoma (1); Stroke (1); thoracic aortic aneurysm (1); Type 2 Diabetes Mellitus (1).